ACE (angiotensin I converting enzyme)
Diseases named in the same sentence as ACE in open-access papers (continued):
Sharing a sentence is not in itself a finding about the gene and the disease.
Hypertension (continued). "The primary goal of this review article was to determine whether the three RAAS-associated SNPs, Renin-rs16853055, AGT-rs3789678 and ACE-rs4305 are genetically linked to the development of hypertension in preeclampsia." (PMID 38411777, 2024). "In addition, certain gut bacteria produce bioactive peptides that inhibit angiotensin-converting enzyme (ACE), helping to lower blood pressure and reduce the risk of hypertension." (PMID 39280497, 2024). "The ACE gene, for example, is involved in blood pressure regulation, and certain variants may predispose individuals to hypertension, a known risk factor for stroke." (PMID 39497863, 2024). "ACE levels in the kidneys and heart are generally at moderate levels and an increase in levels(independent of serum ACE) significantly increase the rate of angiotensin II formation that can cause hypertension." (PMID 39666621, 2024). "Therefore, this study aimed to determine the association between the ACE I/D polymorphism and hypertension among patients attending Tamale Central Hospital, Tamale Ghana." (PMID 39666621, 2024). "The ACE gene comprises 26 exons and has many polymorphisms, notably an insertion or deletion (I/D) of a 276 bp Alu repetitive sequence in intron 16 which has been reported to influence levels of ACE, thus leading to the postulation that ACE I/D is a possible cause in the development of hypertension." (PMID 39666621, 2024). "Thus, the present study aims to explore the distribution and association of ACE polymorphisms with hypertension among Ghanaian patients and corresponding healthy controls were explored in this study." (PMID 39666621, 2024). "Furthermore, ACE inhibition slows the progression of kidney disease associated with hypertension or diabetes." (PMID 39046229, 2024). "Hypertension is one of the main risk factors of coronary ectasia, therefore the use of anti-hypertensive treatment such as ACE inhibitors is justified since they may prevent the progression of coronary dilation by reducing intramural pressure." (PMID 38983998, 2024). "Excessive ACE expression and activity have been linked to the pathogenesis of hypertension." (PMID 39598284, 2024). "As such, further research on arterial hypertension treatment, with a particular emphasis on the use of ACE inhibitors, may contribute to reducing the risk of developing kidney cancer and/or improving the chances of already-diagnosed patients." (PMID 39766039, 2024). "Both in the primary and secondary forms of hypertension, those conditions which are associated with high renin activity may lead to oversaturation of ACE." (PMID 39684795, 2024). "In conclusion, ACE polymorphisms have been previously associated with an increased hypertension risk; hence, they could serve as biomarkers for hypertension predisposition." (PMID 37964928, 2023). "In this regard, it has recently been shown that mice with renal angiotensin I-converting enzyme (ACE) deficiency but normal plasma ACE activity were protected against angiotensin II-induced as well as N(ω)-nitro-L-arginine methyl ester (L-NAME)-induced hypertension." (PMID 36520238, 2023). "The ACE gene I/D polymorphism could therefore be employed as a biomarker for the early detection of hypertension consequences such as Type II diabetes and metabolic syndrome." (PMID 37200278, 2023). "However, the influence of the ACE gene polymorphism on the anthropometric and biochemical parameters of hypertension patients remains unresolved." (PMID 37200278, 2023). "In fact, studies indicate that there is an elevated level of ACE in older patients with hypertension, which may increase their susceptibility to infection." (PMID 37512012, 2023). "Also, an ACE insertion/deletion polymorphism exists in the human genome, which is involved in the occurrence and development of many diseases, including hypertension, heart failure, and sarcoidosis." (PMID 37868968, 2023).
Hypertension (continued). "Hemoglobin, insulin, diuretics, anticoagulation, and β-blockers were associated with higher bilirubin concentrations, whereas the prescription of ASA and ACE inhibitors, hypertension, triglycerides, and HDL cholesterol were associated with a lowering in bilirubin." (PMID 37107322, 2023). "Conversely, many were receiving drugs which are known to limit NO resistance, such as ACE-inhibitors for management of hypertension, heart failure, or coronary risk, perhexiline for stable severe angina pectoris, and statins for management of hypercholesterolaemia." (PMID 37298225, 2023). "ACE inhibitors and ARBs are used to treat hypertension, which causes ACE2 to be unregulated." (PMID 37308887, 2023). "In Latin America, hypertension prevalence is increasing due to various factors, including age, the adoption of a “Westernized” diet, and potential genetic predisposition factors involving the ACE gene." (PMID 37964928, 2023). "In the PPCM group, elevated ACE levels in the ACE DD genotype may be associated with the incidence of hypertension." (PMID 37089887, 2023). "Furthermore, ACE inhibitors as antihypertensive are linked between hypertension and COVID-19 severity as ACE2 serves a role in SARS infections." (PMID 36900756, 2023). "Antihypertensives, such as ACE inhibitors, may be prescribed more commonly in young people as both stress and other conditions, such as obesity, increase the risk for hypertension." (PMID 37933755, 2023). "ACE insertion and deletion polymorphism is associated with the occurrence of myocardial infarction, cardiovascular disease, left ventricular hypertrophy, microalbuminuria, and pregnancy hypertensive disorders." (PMID 37389408, 2023). "The DD genotype is associated with high ACE serum activity, therefore, this genotype could be associated with high blood pressure." (PMID 37948561, 2023). "In the present study, we identified that eNOS Glu298Asp, AGT M234T, and ACE I/D polymorphisms were associated with essential hypertension generated probably by the presence of endothelial dysfunction and vasopressor effect, hyperplasia, and hypertrophy of smooth muscle cells." (PMID 36845669, 2023). "Angiotensin-converting enzyme (ACE), a central component of the renin-angiotensin system, and its insertion/deletion (I/D) gene polymorphism have been linked to hypertension, increased cardiovascular risk, obesity and diabetes, all comorbidities strongly associated with adverse COVID-19 outcome." (PMID 36555850, 2022). "In the early detection of DKD, multi-factorial interventions targeting major risk factors (hyperglycemia, hypertension, dyslipidemia, and smoking) and the use of drugs with renoprotective effects (ACE inhibitors and/or ARBs) can reduce the progression of nephropathy." (PMID 36071835, 2022). "Therefore, the ACE inhibition is associated with the hypertension prevention through the ACE-I peptide consumption, given that ACE is responsible for blood vessel vasoconstriction, by converting angiotensin I (inactive form) to angiotensin II (active form)." (PMID 36496578, 2022). "The influence of ACE gene polymorphisms on hypertension is under controversy." (PMID 36355860, 2022). "For example, those with ACE gene polymorphism may respond better to anti-aldosterone treatment for hypertension or blockade of different aspects of the RAAS, hence may benefit more from this class of treatment." (PMID 36246876, 2022). "ACE is a key enzyme that can cause hypertension symptoms and lead to various diseases." (PMID 36704789, 2022). "As a result, the ACE gene I/D polymorphism might be used as a biomarker for early diagnosis and detection of hypertension and prevention of its complication." (PMID 36355860, 2022). "Therefore, this study aimed to determine the association of ACE gene I/D polymorphism with the risk of hypertension among essential hypertension patients at the University of Gondar Comprehensive Specialized Hospital, Gondar, Ethiopia." (PMID 36355860, 2022).
Hypertension (continued). "ACE inhibitors are essential in the treatment for both high and low risk hypertension, and combination therapies such as “polypill” incorporate ACE inhibitors (enalapril) along with non-steroidal anti-inflammatory drugs (NSAID; aspirin), statins (atorvastatin) and diuretics (hydrochlorothiazide)." (PMID 36232463, 2022). "Methionine can significantly increase the concentration of ACE in blood and cause hypertension." (PMID 35954098, 2022). "However, the association of insertion/deletion polymorphism of the angiotensin-converting enzyme (ACE) gene with essential hypertension is controversial yet, and there is a limited number of publications among the Ethiopian population." (PMID 36355860, 2022). "Finally, we were interested in understanding the effect of melon varieties on inhibition of ACE, which is linked to hypertension and cardio-protection." (PMID 34579288, 2021). "High producer of ACE, the DD genotype has been associated with susceptibility to hypertension." (PMID 34834450, 2021). "In addition, the D/D genotype of ACE along with some classical risk factors (hypertension, obesity, diabetes and dyslipidemia) further increase the frequency of developing CAD." (PMID 34834033, 2021). "Furthermore, the haplotype containing the A allele of rs4353 was reportedly related to increased serum concentrations of ACE and increased hypertension risk." (PMID 34451921, 2021). "Genetic polymorphisms in ACE, such as rs4343, rs4341 and the ACE I/D polymorphism, have been shown to affect ACE levels and activity, and confer susceptibility to hypertension, type 2 diabetes, overweight, nephropathy and certain cardiovascular and autoimmune diseases." (PMID 34489863, 2021). "It is well-known that CAD is a disease of older adults with risk factors like hypertension, hyperlipidemia, smoking, or diabetes mellitus; however, studies have shown that ACE DD, ACE ID, and AGT MM genotypes are considered independent risk factors of premature CAD." (PMID 33907634, 2021). "Furthermore, the link between hypertension and COVID-19 severity is also linked to the use of ACE inhibitors as ACE2 serves a role in SARS infections." (PMID 34577801, 2021). "The relationship between ACE inhibitors and ARBs and risk of COVID-19 need to be clarified as a large proportion of patients with hypertension, type 2 diabetes, heart failure, and chronic kidney disease, all of which are considered risk factors for COVID-19, are currently prescribed these drugs." (PMID 33722197, 2021). "Likewise, a new approach for diabetic management involves inhibition of the carbohydrate-hydrolyzing enzymes, α-amylase and α-glucosidase, while prevention of hypertension is associated with control of the angiotensin-converting enzyme (ACE)." (PMID 33429899, 2021). "Thus, we investigated the association of two ACE polymorphisms involved in diabetes and hypertension (rs4341 and rs4343) with COVID-19 outcome in patients from La Rioja." (PMID 34489863, 2021). "Angiotensin-converting enzyme (ACE) converts angiotensin I to angiotensin II, leading to vasoconstriction and increased blood pressure; thereby, ACE inhibition could reduce the risk of hypertension." (PMID 34451608, 2021). "In one study, the addition of spironolactone or losartan to ACE inhibitor therapy in patients with hypertension, diabetes, and albuminuria was associated with significant increases in serum potassium level compared to the outcome in the placebo group (p < 0.0001 and p = 0.03, respectively)." (PMID 33214722, 2021). "Several studies have demonstrated an association between hypertension and ACE gene." (PMID 35283964, 2021). "Another limitation of the usefulness of ACE serum levels as diagnostic test for OS is the abolition of ACE serum activity in patients taking angiotensin-converting enzyme inhibitors (ACEIs) to treat systemic hypertension." (PMID 33805490, 2021).
Hypertension (continued). "The present study was undertaken to test the hypothesis that male sex and high blood pressure are associated with ACE/ACE2 imbalance in the lungs." (PMID 34751382, 2021). "The present study tested the hypothesis that male sex and high blood pressure are associated with ACE/ACE2 imbalance in the lungs." (PMID 34751382, 2021). "Moreover, among 1,128 hospitalized COVID-19 patients with hypertension from Hubei, China, the inpatient use of ACE inhibitors/ARB was reported to be associated with lower risk of all-cause mortality compared with ACE inhibitors/ARB non-users." (PMID 33195473, 2020). "Synthetic ACE inhibitors such as captroptril, enalapril, or ramipryl are commonly used as drugs in the treatment of hypertension, although they may cause serious side effects such as dry cough, dysgeusia, and angioedema." (PMID 32471271, 2020). "The importance assumed by research focused on ACE biochemistry, physiology and pharmacology is closely linked to the clinical effectiveness showed by ACE inhibitors in the treatment of cardiovascular disease, particularly arterial hypertension and congestive heart failure." (PMID 33195436, 2020). "Consistently, based on a large-scale retrospective study, in-hospital use of ACE inhibitors/ARBs was associated with a lower risk of 28-day death among hospitalized patients with COVID-19 and coexisting hypertension, coronary artery disease and hypertension combined with coronary artery disease." (PMID 33203141, 2020). "ACE2 is upregulated in patients treated with ACE inhibitors thus it is thought that patients with hypertension receiving antihormonal agents might be at higher risk of infection with the COVID-19." (PMID 32412310, 2020). "In addition, hypertension is associated with a variety of mechanisms, such as ACE inhibition in RAS, nitric oxide bioavailability, and regulation of endothelium-dependent relaxation." (PMID 32325920, 2020). "There are two main mechanisms by which ACE causes hypertension." (PMID 32210030, 2020). "Inhibitors of ACE activity are commonly used as drugs in hypertension treatment, but they may cause serious side effects, e.g., cough, rush, or edema." (PMID 32610520, 2020). "On one side, some asked whether the therapy should be discontinued during SARS-Cov-2 pandemic because COVID-19 was strongly associated with hypertension, which is frequently treated with ARBs and ACE inhibitors." (PMID 32579597, 2020). "Synthetic ACE inhibitors are commonly used as drugs in the treatment of hypertension, but they may cause serious side effects such as cough, rash, or angioedema." (PMID 32630448, 2020). "Indeed, we found that ginseng intake decreased the levels of cytokines, including IL-1β, IL-6, and TNF-α, and factors associated with high blood pressure, including ACE activity and angiotensin II." (PMID 32727012, 2020). "Early ACE inhibition may have an important role in the reversal of initial impairments of cognitive function associated with hypertension-induced vascular alterations." (PMID 31441902, 2019). "In gender based study, ACE DD genotype was associated with hypertension in males." (PMID 30333281, 2019). "In heart disease, studies found that pomegranate peel extract may alleviate CHD caused by hypertension by reducing coronary angiotensin-converting enzyme (ACE), OS, and vascular remodeling, which also occurs in linagliptin." (PMID 32148646, 2019). "Our study suggests that ACE inhibitors might serve as a potential agent for the reversal of cognitive alterations induced by initial vascular damage associated with early-stage hypertension." (PMID 31441902, 2019). "Although the use of ACE inhibitors and ARBs are associated with reduction of BP in HD patients limited literature is available on the evaluation of factors associated with pre-dialysis controlled hypertension among euvolemic hemodialysis patients." (PMID 31114693, 2019).
Hypertension (continued). "In addition, very low hemorphin levels were recently reported in obese and diabetic patients that are linked to hypertension and cardiovascular risks suggesting beneficial effects of hemorphins on the inhibition of ACE." (PMID 31708782, 2019). "The two effects together caused by ACE inhibitors result in a relief of hypertension." (PMID 30453595, 2018). "These variables showed a trend towards statistical significance with an independent association between hypertension and the difference in apical twist (regression coefficient of 0.34; p = 0.088), and in the use of an ACE inhibitor or ARB versus net twist (regression coefficient of 0.34; p = 0.09)." (PMID 29750229, 2018). "Also, as inhibitors of ACE and renin, they can be further investigated as natural agents for managing hypertension, which is a strong risk factor for stroke." (PMID 30349677, 2018). "Local causes include candidiasis, lichen planus, herpetic infection, and xerostomia, and systemic causes include use of specific medications (e.g., angiotensin‐converting enzyme (ACE) inhibitor for hypertension therapy), hematological causes, nutritional deficiencies, and Sjogren's syndrome." (PMID 30194771, 2018). "Antihypertensive drugs are prescribed mainly to reduce the morbidity and mortality caused by hypertension and its complications, while we observed that preoperative application of calcium antagonists and ACE inhibitors regimens is meaningful risk to POAF (P < 0.05)." (PMID 28286753, 2017). "Recent findings have indicated possible associations of hypertension with AD progression, and suggest that angiotensin converting enzyme (ACE) inhibitors with potential to pass through the blood brain barrier (BBB) may reduce the risk of AD." (PMID 28158298, 2017). "The ACE D variant is associated with increased production of ACE suggesting that perhaps ACE inhibitor drugs (already available for other conditions such as hypertension) may provide another treatment option for this subgroup of patients." (PMID 28100233, 2017). "However, the presence of ACE D allele increased the risk of hypertension in ESRD patients by 2.14-fold (P=0.036)." (PMID 28447048, 2017). "The aim of the present cross-sectional study was to investigate if polymorphisms of the RAS genes AGT, AGTR1, and ACE might be associated with an increased risk for higher blood pressure and hypertension in the Lithuanian children population." (PMID 28903744, 2017). "Many clinical trials have reported that omapatrilat, which inhibits various proteases including neprilysin and angiotensin-converting enzyme (ACE), may increase the risk of angioedema when it is used to treat hypertension." (PMID 29296218, 2017). "The D allele of the ACE gene was associated with essential hypertension in different populations." (PMID 28938719, 2017). "Thus, association of ACE I/D polymorphism with hypertension in the currently studied subjects cannot be suggested strongly enough." (PMID 27777603, 2016). "Further complicating investigation of the mechanism underlying the pathogenesis of hypertension are racial differences in the effectiveness of the various classes of antihypertensives, including the response to β-blockers, ACE inhibitors, and ARBs." (PMID 27037223, 2016). "Therefore, the aim of the present work was to investigate the association of obesity and its related disorders, namely hypertension, insulin resistance and MetS, with ACE I/D polymorphism in Egyptian females comparing it with Arabic and African studies." (PMID 27777603, 2016). "It has been hypothesised that the concurrent treatment of hypertension with angiotensin converting enzyme (ACE) inhibitors in patients with CSDH might lower the risk of recurrence after surgery." (PMID 27213133, 2016). "Notably, we found that the significant association between ACE DD genotype and hypertension was obesity status dependent." (PMID 26491214, 2015).